KRT15 (keratin 15)
Synonyms: K15; CK15; K1CO
Tractability: PROTAC: UniProt records ubiquitination sites on it; ubiquitination databases record sites on it.
Gene: Protein-coding gene on chromosome 17 (41,513,745 to 41,522,529, reverse strand). Ensembl gene ENSG00000171346.
Subcellular location (Human Protein Atlas): Intermediate filaments; Nucleoplasm
Pathways (Reactome):
Developmental Biology: Differentiation of Keratinocytes in Interfollicular Epidermis in Mammalian Skin; Formation of the cornified envelope; Keratinization
Gene Ontology:
Molecular function: protein binding; scaffold protein binding; structural constituent of cytoskeleton; structural constituent of skin epidermis; structural molecule activity
Biological process: negative regulation of epithelial cell differentiation; epidermis development; epithelial cell differentiation; intermediate filament organization; morphogenesis of an epithelium; negative regulation of keratinocyte differentiation; wound healing
Cellular component: extracellular exosome; intermediate filament cytoskeleton; keratin filament; nucleus; cytoskeleton; cytosol; intermediate filament
Genetic constraint (gnomAD): Loss-of-function variants: 45 observed, 46.86 expected, observed/expected ratio (o/e) 0.96, 90% interval 0.75 to 1.23. The upper end of that interval is the gene's LOEUF score, 1.23, which puts it in group 5 of 6, group 1 being the genes least tolerant of losing a copy. Missense variants: 582 observed, 602.51 expected, observed/expected ratio (o/e) 0.97, 90% interval 0.9 to 1.03. Synonymous variants: 219 observed, 239.33 expected, observed/expected ratio (o/e) 0.92, 90% interval 0.82 to 1.02.
Homologues: Orthologues: chimpanzee KRT15 (98% identical), mouse Krt15 (88% identical), rat Krt15 (87% identical), pig KRT15 (80% identical), rabbit KRT15 (73% identical). Paralogues in human: KRT13 (73% identical), KRT14 (66% identical), KRT16 (66% identical), KRT17 (60% identical), KRT10 (57% identical), KRT19 (57% identical), KRT12 (54% identical), KRT24 (54% identical), KRT9 (52% identical), KRT27 (51% identical), KRT28 (50% identical), KRT25 (48% identical), and 56 more.
Diseases named in the same sentence as KRT15 in open-access papers:
KRT15 is named in the same sentence as 107 diseases in open-access papers, as found by Europe PMC text mining. Sharing a sentence is not in itself a finding about the gene and the disease. The quoted sentences say what the papers report.
breast carcinoma (17 papers, 2008 to 2025). "While PTPRR is a member of the protein tyrosine phosphatase (PTP) family, which is known to be related with prostate cancer, KRT15 is a member of the keratin gene family, which is known to be associated with breast cancer and lung cancer." (PMID 29100492, 2017). "However, a low expression level of KRT15 is significantly linked to a poorer prognosis in breast cancer." (PMID 39770478, 2024). "Our data suggests that KRT15 might be a tumour suppressor gene and could be associated with longer overall survival of patients with breast cancer." (PMID 37842046, 2023). "We found 11 genes (2 stage-III salient genes and 9 stage-IV salient genes) annotated as ‘cancer related genes’, of which two stage-IV salient markers, namely EGR3 and KRT15, were specifically noted as prognostic markers of breast cancer." (PMID 41048341, 2025). "In this study, up-regulation of Keratin 17 (KRT17) and down-regulation of Keratin 15 (KRT15) were observed in breast cancer." (PMID 20543960, 2010). "While there is little information on the role of KRT15 in breast cancer, KRT17 expression was studied in 600 breast tumors and was shown to be associated with poor clinical outcome." (PMID 20543960, 2010). "Moreover, the KRT6B and KRT15 were reported as the markers of basal-like breast cancers." (PMID 34795689, 2021). "Notably, the genes LDHB, MMP7, KRT5, KRT14 and KRT15, which were significantly upregulated in the PIPET_Basal subpopulation, are recognized as specific biomarkers of the basal-like molecular subtype or genes typically highly expressed in basal-like breast cancer." (PMID 38819254, 2024). "Moreover, KRT15, MIA, and TP63 levels significantly decreased in breast cancer cells." (PMID 37842046, 2023).
squamous cell carcinoma (9 papers, 2012 to 2023). A carcinoma arising from squamous epithelial cells. "An increased expression of HB marker keratin 19 (K19) has been observed in human squamous cell carcinomas (SCCs), whereas basal cell carcinomas and trichoblastomas were shown to up-regulate the expression of the HB marker keratin 15 (K15)." (PMID 32423907, 2020). "This comparison showed an overlap of five genes (ETV4 (tumor non-malignant signature), STK32A, SPINK1, GOLT1A, KRT6A (adenocarcinomas—squamous cell carcinomas signature)) in the first case, and an overlap in one (KRT15) of the three most prominent genes in the second case." (PMID 36832225, 2023).
prostate carcinoma (8 papers, 2006 to 2025). A carcinoma that arises from epithelial cells of the prostate gland. "MT1G, MSMB, SLC22A3, COMP and KRT15 have also been associated with aggressive and/or poor clinical outcome in prostate cancer." (PMID 36661662, 2022). "We found that the genes SLC14A1, MSMB, KRT23, and KRT15 are primarily enriched in “prostate cancer” signaling pathway." (PMID 40260298, 2025). "KRT15 is downregulated in the progression of normal prostate tissue to prostate cancer and further to lymph node metastasis." (PMID 34209195, 2021). "Our study reveals that SLC14A1, ARHGEF38, NEFH, MSMB, KRT23, and KRT15 are potential diagnostic biomarkers for prostate cancer, among which MSMB may play a protective role in prostate cancer." (PMID 40260298, 2025). "KRT15, a type I keratin, has been shown to be highly expressed in oesophageal carcinoma, colorectal cancer, and gastric cancer, whereas it is down-regulated in breast and prostate cancers." (PMID 37842046, 2023). "Conversely, in the other study, KRT8, KRT15, KRT19, KRT34, and KRT80 were found to be enriched in African American prostate cancer samples." (PMID 40104216, 2025). "However, KRT15 expression levels were not statistically significant in AA cancer patients compared with EA prostate cancer patients (data not shown)." (PMID 36033462, 2022).
basal cell carcinoma (7 papers, 2012 to 2022). A carcinoma involving the basal cells. "The origin of basal cell carcinoma is still unknown; although an X-ray tracking assay has confirmed follicular bulge stem cells expressing keratin 15 being responsible for basal cell carcinoma." (PMID 24451143, 2014).
melanoma (7 papers, 2016 to 2025). A malignant, usually aggressive tumor composed of atypical, neoplastic melanocytes. "For example, KRT15 is present in the adult and fetal human skin of hair-bearing, non-hair-bearing, and palmoplantar regions and is coordinately expressed with melanoma-associated chondroitin sulfate proteoglycan." (PMID 32934956, 2020). "The markers evaluated include cytokeratin 15 (K15), α6 integrin, and melanoma-associated chondroitin sulfate (MCSP)." (PMID 27375744, 2016). "We also observed a reduced expression of KRT15 in cells located in the dermal compared to the epidermal melanoma cells according to the depth of invasion." (PMID 37602975, 2023). "Moreover, LM511 supports basal cells by sustaining stem and progenitor cells, including melanoma-associated chondroitin sulphate proteoglycan (MCSP) and keratin 15 (K15)-positive cells." (PMID 40399946, 2025). "In addition, KRT17 and KRT15 were up-regulated and demethylated in the eIF6-high expressed melanoma, suggesting that DNA demethylation was a potential transcription regulation mechanism of eIF6." (PMID 35707354, 2022). "KRT15 also correlates with the tumor stage and poor survival in melanoma patients." (PMID 33441834, 2021). "In our study, the expression of KRT15 is higher in primary melanoma than in metastatic melanoma." (PMID 33441834, 2021). "Expression profiles of FABP5, IVL, KRT6A, KRT15, KRT16, and TIMP2 provide clues of prognostic implications, which might help us evaluate malignant potential of nevus and underlying carcinogenesis progress from melanocytic nevus to melanoma." (PMID 32934956, 2020). "Transcription profiles of FABP5, IVL, KRT6A, KRT15, KRT16, and TIMP2 provided clues of prognostic implications, which might help us evaluate malignant potential of nevus and underlying carcinogenesis progress from melanocytic nevus to melanoma." (PMID 32934956, 2020). "Further, alterations in the expression profiles of FABP5, IVL, KRT6A, KRT15, KRT16, and TIMP2 were significantly associated with worse prognosis, indicating that these hub genes may participate in the aggressive transformation from a nevus to malignant melanoma." (PMID 32934956, 2020). "In addition, survival curves indicated that six hub genes, including FABP5, IVL, KRT6A, KRT15, KRT16, and TIMP2, were significant prognostic signatures for CM and of significant value to predict transformation from nevi to melanoma." (PMID 32934956, 2020).
psoriasis (7 papers, 2018 to 2026). An autoimmune condition characterized by red, well-delineated plaques with silvery scales that are usually on the extensor surfaces and scalp. "The expression of many genes known to be associated with psoriasis, including Lce3f, Sprr2b, Krt15, S100a8, S100a9, Il17a, Il17f, Il18, Il20, Il22, and Ccl20, was downregulated in the skin of IMQ-treated Camk4−/− mice compared with those of IMQ-treated Camk4+/+ mice." (PMID 35869084, 2022). "The expression of KRT15 in pretreatment psoriasis lesional skin was localized to the basal layer in pretreatment psoriasis lesional skin." (PMID 37781383, 2023). "In contrast to the inflammatory mediators induced by IL-17, the expression of the KC stem cell marker (KRT15) was decreased in pretreatment psoriasis lesional skin KCs compared to control skin KCs (p < 0.05)." (PMID 37781383, 2023). "After systemic IL-17A blockade, the expression of KRT15 was increased in posttreatment psoriasis lesional skin KCs compared to pretreatment psoriasis lesional skin KCs (p < 0.05)." (PMID 37781383, 2023). "After IL-17A blockade, KC expression of KRT15 in S. basale increased in posttreatment psoriasis lesional skin compared to pretreatment psoriasis lesional skin (p < 0.05)." (PMID 37781383, 2023). "To assess whether FZHFZY influences epidermal differentiation in the skin of mice with IMQ-induced psoriasis, we detected the expression of loricrin, filaggrin, involucrin, keratin 5, keratin 14 and keratin 15 in the skin by RT-PCR and western blotting." (PMID 34456715, 2021). "KRT15, KRT24, KRT31, KRT37, KRT78 are differentially expressed in psoriasis, while KRT5 and KRT14 are specific for AD." (PMID 35874668, 2022). "In our study, there is downregulated expression of loricrin, filaggrin and involucrin, but elevated expression of keratin 5, keratin 14 and keratin 15 in IL-17A/IL-22/IFN-γ/TNF-α–induced HaCaT cells and in mice with IMQ-induced psoriasis." (PMID 34456715, 2021).
papilloma (6 papers, 2013 to 2021). A benign epithelial neoplasm that projects above the surrounding epithelial surface and consists of villous or arborescent outgrowths of fibrovascular stroma. "We and others have demonstrated a role for keratin 15 (K15)-expressing hair follicle (HF) progenitor cells in skin tumorigenesis and have shown a contribution by both K15-positive and negative progenitors in papilloma development." (PMID 30546048, 2018).
colorectal cancer (4 papers, 2022 to 2024). A primary or metastatic malignant neoplasm that affects the colon or rectum. "KRT15 can promote the migration and invasion of colorectal cancer cells." (PMID 39770478, 2024). "Moreover, KRT15 was demonstrated to promote migration and invasion of colorectal cancer cells partly via β-catenin-mediated signaling; β-catenin, which regulates cell-cell adhesions (Brembeck, Rosario & Birchmeier, 2006), was also found to be semantically related with KRT15." (PMID 36949761, 2023). "However, highly expressed KRT15 protein may contribute to esophageal carcinoma progression, whereas overexpression of KRT18 in colorectal cancer exerts an oncogenic role." (PMID 35328735, 2022).
esophageal carcinoma (4 papers, 2021 to 2025). A primary or metastatic malignant neoplasm involving the esophagus. "In esophageal carcinoma, the high expression of KRT15 is closely related to tumor invasiveness, metastasis, and poor prognosis." (PMID 39354287, 2025). "However, KRT13 and KRT15 were found to be down-regulated in TCGA-derived esophageal carcinoma samples." (PMID 36949761, 2023).
alopecia (3 papers, 2013 to 2021). Hair loss usually from the scalp. "We also did not observe the presence of perifollicular lymphocyte-rich infiltrates and the dermal scarring that was associated with the alopecia observed in the Krt15-Cre-driven Pparg knockout mice." (PMID 34445339, 2021). "Tissue-specific deletion of Pparg in bulb stem cells (Krt15-promoter dependent Cre) resulted in a scarring alopecia and sebaceous gland hypoplasia that resembles human lichen planopilaris." (PMID 34445339, 2021).
bladder cancer (3 papers, 2003 to 2021). "Among the top DMRs, we note many overlapping with genes known to be involved in bladder cancer, such as FGFR3, GATA3, KRT15, and KRT5." (PMID 33397444, 2021).
breast invasive carcinoma (3 papers, 2021 to 2025). "Low expression of KRT15 in breast invasive carcinoma was associated with unfavorable prognosis." (PMID 36949761, 2023).
cicatricial alopecia (3 papers, 2012 to 2022). Scarring hair loss, also known as cicatricial alopecia, is the loss of hair which is accompanied with scarring. "A previous study revealed that PPAR-γ signaling was critical for the survival of eHFSCs in mice, suggesting that the loss of this receptor targeted by the keratin 15 (K15) promoter in these stem cells leads to cicatricial alopecia-like manifestations." (PMID 35957858, 2022). "Cytokeratin 15 (CK15), a marker of stem cells, has been used to show the bulge region involvement in the scarring process in primary cicatricial alopecia and DLE." (PMID 22888407, 2012).
cyst (3 papers, 2020 to 2025). A sac-like closed membranous structure that may be empty or contain fluid or amorphous material. "In cKO P21 HFs, KRT15+ cells (i.e., potential SCs) were located specifically in the bulb area of the cyst, whereas in the controls, faint staining of KRT15+ cells was detected within the basement membrane of the epidermis and in the bulge." (PMID 35247391, 2022).
keratoconus (3 papers, 2021 to 2025). A degenerative, structural disorder of the eye, characterized by a cone-shaped protrusion of the cornea. "Our study further confirmed that feature genes such as the S100A8/A9 complex, KRT14, and KRT15 were significantly associated with the increased risk of keratoconus, and alterations in these genes were closely related to corneal structural stability, mechanical strength, and disease progression." (PMID 40426861, 2025).
lichen planopilaris (3 papers, 2013 to 2025). Lichen planopilaris (LPP) is an inflammatory condition that causes patchy hair loss, mainly on the scalp. "In conditions such as lichen planopilaris, when immune privilege in the bulge collapses, T cells infiltrate the area and eradicate KRT15+ and CD200+ stem cells, underscoring the sensitivity of these markers to inflammation-driven damage." (PMID 40361941, 2025). "Immunostaining of PCA tissues, such as lichen planopilaris (LPP) and chronic cutaneous lupus erythematosus (CCLE), also shows decreased levels of keratin-15, which is almost exclusively limited to the bulge region." (PMID 29333153, 2017).
lung carcinoma (3 papers, 2015 to 2017). "We selected 6 loci displaying significant differential cirDNA modification in the microarray analysis (Rab3a, Atp6v0c, B4galnt1, Slc1a1, Ttl and Krt15) and whose corresponding genes have been reported as associated to lung cancer phenotypes." (PMID 25415227, 2015). "The top hubgene KRT15 has been implicated in breast and lung cancers." (PMID 25938420, 2015).
sebaceous gland tumours (3 papers, 2015 to 2019). "Like K14ΔNLef1 mice, mice overexpressing ΔNLef1 under the control of the Krt15 promoter (which labels HF bulge cells) develop sebaceous tumors." (PMID 30886049, 2019).
cervical cancer (2 papers, 2025). A primary or metastatic malignant neoplasm involving the cervix. "We performed a similar analysis on our RNA-seq analysis and identified several genes that are also implicated in cervical cancer and HPV infection, including Krt16 (up), Krt6a (up), Hmox1 (up), and Krt15 (down)." (PMID 41165329, 2025). "While the importance of KRT8 and KRT15 is rarely reported in cervical cancer, these findings offer opportunities to identify new therapeutic targets and develop targeted treatment strategies." (PMID 39354287, 2025). "KRT8 and KRT15 increase progressively with the development of cervical cancer." (PMID 39354287, 2025).
chordoma (2 papers, 2010 to 2023). Chordomas are rare malignant tumors arising from embryonic remnants of the notochord in axial skeleton. "For example, KRT15 was differentially expressed in chordoma versus mesenchymal tumors and chordoma versus IVD, but not chordoma versus normal tissue." (PMID 21253487, 2010).
dermatitis (2 papers, 2009 to 2026). An inflammatory process affecting the skin. "With the notable exception of KRT15, initial insight about the functional importance of the keratin genes expressed in the epidermis was inferred from the phenotype of transgenic mouse models and/or individuals suffering from rare genetic skin disorders." (PMID 41511042, 2026).
esophageal squamous cell carcinoma (2 papers, 2025). Esophageal squamous cell carcinoma (ESCC) is a type of esophageal carcinoma (EC) that can affect any part of the esophagus, but is usually located in the upper or middle third. "KRT15 plays a significant role in the progression from high-grade intraepithelial neoplasia to esophageal squamous cell carcinoma, which is associated with tumor initiation and early development." (PMID 39354287, 2025). "The reduced expression of KRT15 in esophageal squamous cell carcinoma tissues and patient serum suggests its important role in the development of esophageal squamous cell carcinoma." (PMID 40070828, 2025).
metastatic melanoma (2 papers, 2021 to 2023). A melanoma that has spread from its primary site to another anatomic site. "The protein Keratin 15 (KRT15), which is normally expressed in basal keratinocytes of the epidermis, has also been found to be associated with tumor stage and prognosis in metastatic melanoma patients, with higher expression in primary tumors and loss in metastases." (PMID 37602975, 2023).
metastatic tumors (2 papers, 2007 to 2022). "The results showed that CAFs in metastatic tumors expressed high levels of KRT15, FABP4, S100A8, and COL18A1 and were associated with high enrichment of vasculature development, cell population proliferation, and epithelial cell differentiation." (PMID 36569924, 2022). "However, macrophages in metastatic tumors had high expression of HLA-DQA2, KRT15, S100A8, and S100A9, and GO analysis showed that lipid catabolic process, myeloid leukocyte migration, and the regulation of cell activation were highly enriched." (PMID 36569924, 2022). "Cytokeratins 5 and 15 (KRT5/KRT15), markers of basal cells in prostate glands, show uniform downregulation in all metastatic tumors, confirming the absence of basal epithelial cells." (PMID 17430594, 2007).
oral cancer (2 papers, 2023 to 2026). "Furthermore, the phylogenetically and semantically related KRT13 and KRT15 are also directly associated in oral cancers." (PMID 36949761, 2023).
prostate tumor (2 papers, 2017 to 2022). "In this study, we demonstrated that 255 DEGs were up/down-regulated in prostate tumors compared with BPH tissues; qRT-PCR also confirmed that the DEGs such as ITGBL1, KRT15, TGM4, and HOXA7 genes were up/down-regulated in PCa tissue and cell lines." (PMID 29285211, 2017).